INS (insulin)
Diseases named in the same sentence as INS in open-access papers (continued):
Sharing a sentence is not in itself a finding about the gene and the disease.
Obesity (continued). "Also, a study assessing the impact of L-arginine and selenium supplementation on women with central obesity revealed that selenium markedly reduced fasting insulin levels and enhanced insulin sensitivity, thereby emphasizing its potential utility in addressing obesity-related metabolic disorders." (PMID 40182029, 2025). "To date, a growing body of research has been dedicated to the study of obesity/breast cancer biological link, with the most well‐documented mechanisms involving chronic inflammation, altered adipokine levels, dysregulated hormone signaling, and insulin/growth factor pathways." (PMID 40523654, 2025). "Furthermore, unlike β-cell failure in T2D, IR within the SM is reversible and therefore represents a clinically meaningful therapeutic target to optimise insulin sensitivity and overall metabolic efficiency and flexibility, especially in the context of obesity." (PMID 39997710, 2025). "An important inflammatory pathway linked to NF-κB in obesity is the MEK/ERK signaling cascade, which is co-activated by the same metabolic and cytokine stimuli and synergistically enhances NF-κB–driven transcription, thereby reinforcing chronic adipose inflammation and insulin resistance." (PMID 41463063, 2025). "Additionally, our current findings also suggest differences in the size and location of LDs within skeletal muscle may contribute to differences in insulin‐mediated glucose uptake in a relatively homogeneous cohort of adults with obesity." (PMID 39487600, 2025). "In addition to mechanical effects, obesity might activate bone formation via endocrine mechanisms mediated by insulin, leptin, and estrogen." (PMID 41441007, 2025). "Likewise, kaempferol and rutin have been reported to up-regulate GLUT4 expression, enhance glucose uptake, and improve blood glucose control, glucose tolerance, and insulin sensitivity in obese animal models, with kaempferol demonstrating the strongest antidiabetic and anti-obesity effects." (PMID 41304900, 2025). "Butyrate, a major SCFA, also improves insulin sensitivity and may support obesity treatment." (PMID 40864791, 2025). "Importantly, VAT mass reduction—accompanied by improved insulin sensitivity—is associated with an approximately 25% decrease in circulating RBP4 in non-diabetic individuals with obesity." (PMID 41303567, 2025). "While reductions in cardiac fatty acid oxidation in whole-body MCD KO mice subjected to experimental obesity (via HFD feeding) were associated with improved insulin-stimulated cardiac glucose oxidation, no changes in ex vivo or in vivo cardiac function were observed." (PMID 40663803, 2025). "Moreover, they found that CDK1 and PKCδ may play a critical role in the obesity-to-T2D progression, with elevated levels of these kinases contributing to reduced insulin secretion capacity and increased IR." (PMID 41441338, 2025). "In another study, it was reported that in obesity and obesity-related T2D, circulating acylated ghrelin concentrations increased, while des-acyl ghrelin levels decreased, and Body Mass Index (BMI), waist circumference, and insulin were positively correlated with acyl ghrelin levels." (PMID 40870497, 2025). "Additionally, it has been shown to enhance insulin sensitivity in individuals with obesity." (PMID 40265287, 2025). "Our interesting findings regarding improved glucose tolerance and insulin sensitivity after exosome therapy could be attributed to their role in attenuating HFD-induced obesity, primarily through their protective effect on islets by reducing macrophage infiltration and inflammation." (PMID 41256259, 2025). "However, other studies have suggested that CA derivatives, such as ferulic acid and caffeic acid, exert anti-obesity and hypoglycemic effects by modulating key enzymes involved in adipose tissue lipogenesis and hepatic glucose synthesis, along with stimulating insulin release." (PMID 40869259, 2025).
Obesity (continued). "In general, obesity is associated with dysfunction of the hypothalamic–pituitary–adrenal (HPA) axis with a reduced response to cortisol feedback with the immune system (chronic low-grade inflammation) and dysregulation of metabolic pathways (leptin, insulin, NPY, and ghrelin, among others)." (PMID 41373743, 2025). "Hence, our results might support a potential involvement of this myokine in glucose homeostasis and suggest that METRNL could be a potential predictive biomarker of insulin sensitivity and metabolic flexibility in postmenopausal women with overweight/obesity." (PMID 40806137, 2025). "Leptin is involved in the upregulation of IL-6 and TNF-α, contributing to obesity-related low-grade inflammation, promoting vascular dysfunction by contributing to hypertension, angiogenesis, and atherosclerosis, and interacting with insulin, affecting glucose and lipid metabolism." (PMID 40724644, 2025). "In addition, it has been indicated that the CTRPs promote the initiation and progression of obesity-related metabolic disorders by directly or indirectly regulating a variety of target proteins involved in insulin signaling, inflammatory pathways, and energy metabolism." (PMID 39812542, 2025). "The pathophysiological mechanism behind SIBO and obesity can be explained by alterations in the gut microbiota composition, which may disrupt the production of appetite hormones, energy balance, and insulin secretion, potentially leading to the development of obesity." (PMID 40917089, 2025). "Therefore, we tested the hypothesis that regular mango intake will improve inflammation status in people with overweight/obesity (OW/OB) and chronic low-grade inflammation, resulting in increased insulin sensitivity." (PMID 39940348, 2025). "In addition, Ruminococcus_1 and uncultured_bacterium_f_Muribaculaceae could not only cause lipolysis and fatty acid oxidation, inhibit liver cholesterol synthesis, and alleviate host obesity, but also improve insulin sensitivity." (PMID 39974510, 2025). "It was ascertained that in vivo PTP1B deficiency or silencing can result in enhanced signal transduction of both leptin and insulin, thus improving glucose homeostasis and providing resistance to diet-induced obesity, without causing abnormalities in growth or other vital functions." (PMID 41302504, 2025). "Elevated creatinine may reflect higher levels of creatine, a metabolite whose supplementation has been shown to protect against high-fat diet-induced obesity, enhance insulin sensitivity, improve glucose homeostasis, and promote lipolysis, lipophagy, and thermogenesis in BAT." (PMID 41509418, 2025). "Obesity may reduce vitamin D levels (due to sequestration of vitamin D in fat tissue), and low vitamin D levels might also influence body weight and fat accumulation through effects on metabolism and insulin sensitivity." (PMID 40585599, 2025). "Thus, hyperinsulinemia and hyperleptinemia in the milk of obese mothers, which reflects their insulin and leptin resistance, may possibly expose their infants to developmental programming of obesity in later life." (PMID 40077697, 2025). "Interestingly, postprandial insulin, GIP, and glucose rise h were associated with sensations of satiety exclusively in the wheat-group, advocating for further studies investigating appetite regulation in individuals with overweight and obesity." (PMID 39515756, 2025). "Drug treatments that target NeuroKinin 2 Receptor (NK2R) could be a viable option for fighting obesity by reducing hunger, burning energy, and improving insulin resistance, without causing unwanted side effects." (PMID 40282955, 2025). "Dysregulation of the FTO gene has been linked to various conditions, including obesity, T2D, and PCOS, which contributes to these conditions through its effect on body weight and BMI, in addition to its impact on metabolic factors like IR, insulin sensitivity, serum glucose, and hyperandrogenemia." (PMID 40486662, 2025).
Obesity (continued). "Therefore, obesity and metabolic disorders affect the relationship between metabolically healthy phenotypes and Klotho through mechanisms such as inducing chronic inflammation, interfering with insulin function and abnormal secretion of adipokines." (PMID 40060377, 2025). "-Inverse association with intra-abdominal WAT and obesity.-Inverse association with T2D, mediated by visceral fat content.-Decreases with weight gain.-Increases with weight loss in obese men and women.-Promotes WAT flexibility in women, contributing to improved insulin sensitivity." (PMID 41180177, 2025). "Moreover, obesity is correlated with various post-receptor binding defects in insulin signaling, including compromised generation of second messengers, impaired glucose transport, and disturbances in essential enzymatic pathways involved in glucose utilization." (PMID 40943267, 2025). "Its pathogenesis has been explained by the “second strike hypothesis,” wherein hepatic lipid overload triggered by “insulin resistance,” a “high-fat diet,” “sedentary behavior,” and “obesity” is the first “strike,” and oxidative stress along with inflammation are the second “strike”." (PMID 41458968, 2025). "Various trace elements of essential metals, including zinc, are directly involved in the synthesis, storage, and activity of insulin, forming a specific phenotypic subtype of insulin resistance that may represent one of the mechanistic pathways in the pathogenesis of obesity." (PMID 41465437, 2025). "Collectively, these results suggest that the EcNA intervention may promote metabolic homeostasis in eVAT when compared to EcN, possibly by improving insulin sensitivity and stimulating energy production and expenditure, thereby exerting an anti-obesity effect in eVAT in the MASLD setting." (PMID 40211057, 2025). "This supports the hypothesis that ciliopathies, such as BBS, involve intrinsic defects in leptin and insulin pathways that are exacerbated, rather than solely caused, by obesity." (PMID 40233116, 2025). "Although, per the stratified randomization, the proportion of study participants with overweight or obesity was the same in each study group (43%), unbalanced heterogeneity within the children with overweight or obesity (e.g., wider range of saliva insulin) may be a source of error." (PMID 40557236, 2025). "Specifically, we found that changes in 6MWT correlated with improvements of metabolic parameters, such as insulin, cholesterol, HOMA index and AIP, suggesting that this simple test is able to reveal relevant modifications in the pathogenetic mechanisms underlying obesity-related complications." (PMID 40153416, 2025). "However, this catabolic response differs fundamentally from the effects of long-term diet-induced acidosis: the former reflects a compensatory hypermetabolic state, whereas the latter promotes energy storage and obesity through hormonal suppression, inflammation, and insulin resistance." (PMID 41305607, 2025). "Obesity associated with T2DM further amplifies this process by increasing the production of proinflammatory mediators such as tumor necrosis factor-alpha (TNF-α) and interleukin-6 (IL-6), while reducing adiponectin levels, a hormone with anti-inflammatory and insulin-sensitizing properties." (PMID 41462693, 2025). "Obesity significantly contributes to both the onset and progression of T2DM through mechanisms such as enhanced genetic and epigenetic susceptibility, microenvironmental changes that impair insulin signaling, β-cell dysfunction, and alterations in the microbiome–gut–brain axis." (PMID 41150735, 2025). "Clinical studies in humans have not identified any direct relationships between EPA, DHA and BAT activity, however, consumption of DHA and EPA over 12 weeks improved insulin resistance in individuals with obesity by reducing fasting insulin levels independent of weight loss." (PMID 39087083, 2024).
Obesity (continued). "Finally, we examined in subjects with obesity possible sex differences in other factors which indirectly may influence insulin action in fat cells." (PMID 38491191, 2024). "However, the obesity paradox was substantially weaker in patients receiving insulin treatment." (PMID 37608126, 2024). "Both of them are related to the obesity markers, but they cannot be used as potential predictors for metabolic disturbance in obese prepubertal children; as both of them had insignificant correlations with the metabolic risk factors (WC, BP, FBG, insulin, HOMA-IR, and lipid profile)." (PMID 38216702, 2024). "This is especially important because secreted FABP4 was correlated with obesity-related breast cancer and its secretion from adipocytes in individuals with obesity is correlated with adipocyte hypertrophy, harmful effects on other tissues, and insulin resistance." (PMID 38388800, 2024). "Similar to the current results, an interventional study indicated that in adolescent girls with obesity, aerobic but not resistance exercise is effective for reducing liver fat and visceral adiposity while improving insulin sensitivity, independent of BM loss or calorie restriction." (PMID 39274218, 2024). "Oxidative stress is also a pathogenetic mechanism linking obesity to insulin resistance: inflammatory adipokines released from excessive adipose tissue (especially visceral fat) and excessive free fatty acids result in systematic oxidation and insulin signaling disruption." (PMID 39544693, 2024). "This hypothesis is supported by a study by Dubé and colleagues in which a 16-week exercise program conducted in sedentary subjects with overweight or obesity increased IMF by 21% while improving insulin sensitivity by 21% and decreasing diacylglycerol and ceramide levels." (PMID 38732623, 2024). "Illustratively, the insulin secretion signaling pathway emerges as a central orchestrator of glucose and lipid metabolism, with alterations in this pathway bearing direct consequences for the initiation and progression of cardiometabolic diseases, including obesity, T2D, and dyslipidemia." (PMID 39411310, 2024). "We hypothesised that having a history of obesity (having been overweight but subsequently losing weight) may result in residual defects in insulin action, particularly in adipose tissue, and ultimately may contribute to worse metabolic outcomes upon weight regain." (PMID 38961153, 2024). "In addition to leptin and ghrelin, other physiological factors may influence the impact of SJL in obesity, such as insulin sensitivity, cortisol secretion, intestinal peptides, and alterations in the autonomous nervous system." (PMID 39203711, 2024). "However, in obesity, resistance to both insulin and leptin can develop, impacting uterine function." (PMID 39767708, 2024). "Moreover, although weight loss in women with obesity and PCOS can improve hormonal function, insulin sensitivity, and hyperandrogenism, it is essential to keep in mind the potential harm of placing emphasis on strict weight management in subjects suffering from an ED." (PMID 38612972, 2024). "Furthermore, in the group with obesity, a significant correlation was found between the erythrocyte and insulin value after 2 h of OGTT (p = 0.04, r = 0.4), while HGB correlated with glucose and insulin after 2 h of OGTT (p = 0.018, r = 0.45; p = 0.04, r = 0.44, respectively)." (PMID 39610842, 2024). "Obesity or visceral obesity has been found to potentially contribute to the upregulation of adipocytokines, and heightened inflammatory activity, ultimately leading to diminished insulin sensitivity, dyslipidemia, endothelial dysfunction, development of atherosclerosis, and increased stiffness." (PMID 38549547, 2024).
Obesity (continued). "The obesity mice model reveals the catabolism of BCAA was disrupted which will cause the accumulation of BCAA, and high-level BCAA will promote ATMs M1 polarization and increase the pro-inflammatory cytokines in adipose tissue which will cause the insulin resistance in further." (PMID 39267003, 2024). "While the mechanisms by which Lingguizhugan decoction (LGZGD) intervenes in obesity by improving lipid metabolism, enhancing insulin sensitivity, and reducing inflammatory responses are well-documented, its potential in intestinal microbiota and SCFAs remains unclear." (PMID 39606109, 2024). "It is known that aging alone reduces β-cell proliferation in both humans and mice, and obesity and pre-diabetic conditions may also alter β-cell proliferation and volume; this would be in line with the obese and insulin-resistant phenotype in the Chr4Δ70/Δ70 mice." (PMID 38891115, 2024). "Estimation of other insulin and glucagon regulators like somatostatin and incretins could have also been included to give us a wholesome picture of insulin and glucagon secretion in obesity and in different glucose tolerance states." (PMID 38665134, 2024). "Consequently, an increasing body of literature proposes an alternative approach using obesity biomarkers, such as circulating hormones (e.g., adipokines, insulin, and insulin-like growth factor [IGF-1]), to delineate obesity phenotypes associated with an elevated risk of morbidity and mortality." (PMID 39822775, 2024). "The underlying cause of anovulation in individuals with obesity is poorly defined, and accumulating evidence indicates that hormonal disturbance, insulin resistance, and inflammation may all play a role in the development of ovulation disorders in individuals with obesity." (PMID 38333108, 2024). "In turn, the rs3842729 polymorphism of the INS does not directly affect the risk of obesity or T2D." (PMID 38250713, 2024). "Although weight loss achieved by caloric restriction and/or exercise, lowers insulin resistance, and increases the action of insulin to suppress fatty acid oxidation to a similar degree in individuals with obesity, the role of caloric restriction on mitochondrial physiology is somewhat unclear." (PMID 38561248, 2024). "Individuals with minimal visceral fat and severe obesity may be more insulin sensitive." (PMID 39559714, 2024). "Vaspin plays a protective role in obesity via its insulin-sensitizing and anti-inflammatory effects, and RBP4 is contrarily involved in the development of insulin resistance and associated with total cholesterol and triglyceride levels, contributing to the progress of obesity." (PMID 38256272, 2024). "If this hypothesis is correct, treatment with insulin in women with obesity-T2D might not only correct elevated blood glucose levels (poorly controlled in this group) but could also correct hepcidin levels and lower iron stores, which are linked to alleviated insulin resistance." (PMID 40895225, 2024). "Multiple mechanisms may mediate pro-carcinogenic effects of obesity, including altered adipokine levels, local and systemic inflammation, disruption of insulin and insulin-like growth factor signaling, increased estrogen levels, and alterations of the microbiome." (PMID 41853525, 2024). "Additionally, many patients in the class I and II obesity range (BMI 30–40 kg/m2) in our cohort presented metabolic diseases, likely leading to chronic inflammation, insulin resistance, adipokine dysregulation, and increased production of reactive oxygen species (ROS)." (PMID 38792422, 2024). "In humans, clinical research has rarely addressed the use of colchicine in obesity and MS, with only one pilot randomized clinical trial having been conducted, which identified a beneficial anti-inflammatory effect on endothelial function and the process of insulin resistance in this population." (PMID 39590865, 2024).